TNF (tumor necrosis factor)
Diseases named in the same sentence as TNF in open-access papers (continued):
Sharing a sentence is not in itself a finding about the gene and the disease.
inflammatory bowel disease (continued). "A clinical study showed that antitumor necrosis factor (anti-TNF) could decrease anxiety in inflammatory bowel disease patients." (PMID 36106141, 2022). "Here we report SARS-CoV-2 vaccine-induced immune responses and breakthrough infections in patients with inflammatory bowel disease, who are treated either with the anti-TNF antibody, infliximab, or with vedolizumab targeting a gut-specific anti-integrin that does not impair systemic immunity." (PMID 35296643, 2022). "In 1058 patients with inflammatory bowel disease who underwent therapeutic drug monitoring for both infliximab and adalimumab, those who developed antibodies to a first anti‐TNF were more likely to develop antibodies to a second anti‐TNF, irrespective of drug sequence." (PMID 36039036, 2022). "Co-administration of methotrexate and TNF-α antibody may reduce the rate of ADA formation in inflammatory bowel disease." (PMID 35401191, 2022). "Patients with inflammatory bowel disease (IBD), including Crohn’s disease (CD) and ulcerative colitis (UC), are often treated with immunomodulators and/or biologic therapy such as anti-tumor necrosis factor alpha (TNFα), potentially associated with an increased risk of infection." (PMID 35893835, 2022). "The introduction of biological agents with strong anti-inflammatory action, such as antitumor necrosis factor (TNF) agents, has changed inflammatory bowel disease (IBD) treatment strategy and goals, and has contributed significantly to improve the long-term prognosis of patients." (PMID 35498800, 2022). "The early keywords intravenous cyclosporine, anti-tumor necrosis factor, and controlled trial are all about the treatment of inflammatory bowel disease, while “evidence-based consensus”, “management”, “impact” and “diagnosis” are related to the diagnosis, management, prognosis of the disease." (PMID 35761289, 2022). "Furthermore, Veroniella is a proinflammatory taxon that increases in patients with inflammatory bowel disease and irritable bowel syndrome and promotes the expression of several inflammatory cytokines (TNF-α, IL-6, and IL-1β) in the colon." (PMID 36519162, 2022). "In accordance with the PRISMA guidelines, we queried the Cochrane, PubMed, and Clinicaltrials.org databases from inception till 2020 using the medical subject headings (MeSH) “inflammatory bowel disease”, “anti-TNF”, “heart failure”, and “disease modifying anti-rheumatic drugs”." (PMID 36289474, 2022). "Additionally, as expected, the effect of stimulation with TNF-α, a key mediator in inflammatory bowel disease, resulted in a disturbance of the tight junctions network." (PMID 37520160, 2022). "Furthermore, TNF-α and IFN-γ can cause intestinal mucosal dysfunction in inflammatory bowel disease." (PMID 35576220, 2022). "Here the authors report immune responses and breakthrough infections in twice-vaccinated patients receiving anti-TNF treatments for inflammatory bowel disease, and find dampened vaccine responses that implicate the need of adapted vaccination schedules for these patients." (PMID 35296643, 2022). "TNFα is one of the major inducers of SAA synthesis in the liver, and it has also been shown that the production of SAA is increased in intestinal epithelial cells following TNFα stimulation, possibly contributing to the development of inflammatory bowel disease." (PMID 36045687, 2022). "Besides, a preceding study investigates the correlation between MALT1 expression and clinical features in autoimmune diseases: MALT1 is positively related to CRP, TNF‐α, and IL‐17A in inflammatory bowel disease patients." (PMID 35622982, 2022). "In patients with active inflammatory bowel disease, serum ghrelin concentrations are significantly elevated and positively correlated with serum inflammatory markers, such as tumor necrosis factor-α (TNF-α), C-reactive protein (CRP), erythrocyte sedimentation rate (ESR) and fibrinogen." (PMID 36350879, 2022).
inflammatory bowel disease (continued). "The previous studies showed that clinical use of proinflammatory markers (TLR2, TLR2, TLR4, TNF-α, sTNFR-1, and sTNFR-2) provided a means of evaluating inflammatory diseases such as inflammatory bowel disease, breast cancer, coronary artery disease, chronic heart failure, and type 2 diabetes." (PMID 35425840, 2022). "TNF-α is the central mediator of many autoimmune diseases, including inflammatory bowel diseases." (PMID 35370688, 2022). "In future studies, it may be informative to explore other tissues in the Sost−/− mice, as in a rat model of inflammatory bowel disease, which causes systemic inflammation, osteocytes that co-express SOST and TNFα are increased." (PMID 34502021, 2021). "Tumor necrosis factor alpha (TNF-α) collectively participates in inflammatory bowel disease." (PMID 34334085, 2021). "Related studies have shown that nobiletin can protect the intestinal epithelium barrier by reducing inflammatory cytokines and can reduce duodenal retraction to treat inflammatory bowel disease by inhibiting tumor necrosis factor-α (TNF-α) and the expression of COX-2." (PMID 33868436, 2021). "Notably tumor necrosis factor (TNF) alpha antagonists are particularly useful in inflammatory bowel disease (IBD) such as Crohn's disease (CD) and ulcerative colitis (UC)." (PMID 34703704, 2021). "Interestingly, a pro-inflammatory cytokine cocktail (IL-1β, IL6, TNF-α) reproduced the inflammatory phenotype in non-inflammatory bowel disease organoids, suggesting that some aspect of these diseases can be induced in culture." (PMID 34072095, 2021). "Other potential markers of intestinal inflammation including antitrypsin, eosinophilic protein X, TNFα, or lysozyme have been suggested for diagnosing inflammatory bowel disease, which may be expanded to test for STH attributable intestinal morbidity." (PMID 33554091, 2021). "On the other hand, immunosuppression might even elevate the risk of lymphoma development as it has been shown for the use of thiopurines and/or anti-TNF treatment in inflammatory bowel disease." (PMID 33876323, 2021). "An electronic search was performed in PubMed up to April 2021 using the following algorithm: (“inflammatory bowel disease” OR “ulcerative colitis” OR Crohn) AND (anti-TNF OR antiTNF OR infliximab OR adalimumab OR certolizumab OR golimumab) AND (vedolizumab OR ustekinumab OR tofacitinib)." (PMID 34830595, 2021). "In the case of anti-TNF treatment for inflammatory bowel disease (IBD), would there be a safer, equally effective form of this protein class that might be restricted to the intestinal lamina propria following oral delivery as has been suggested ?" (PMID 34371698, 2021). "Eczema as an adverse effect of anti-TNF-α therapy may occur in approximately 5–20% of patients with inflammatory bowel disease (both CD and UC)." (PMID 33802483, 2021). "Another underlying reason for the better prognosis associated with the usage of anti-TNF agents might be the therapeutic effect of anti-TNF agents for primary diseases such as inflammatory bowel disease." (PMID 34335579, 2021). "Similarly, quercetin was shown to suppress the secretion of TNF-α and interfere with the onset of disease in an inflammatory bowel disease (IBD) model." (PMID 33924384, 2021). "Similarly, increased asymmetric SC self‐renewal divisions were seen in hyperproliferative inflammatory bowel disease in mice, induced by dextran sodium sulfate or TNFα." (PMID 33524216, 2021). "Binding to tm-TNFα can trigger potential biological functions known as “referred signaling,” which may play a role in some therapeutic indications (e.g., inflammatory bowel disease)." (PMID 33669108, 2021). "From in vivo studies, osthole (50 mg/kg) could benefit inflammatory bowel disease by increasing IL-10 and reducing the levels of TNF-α and IL-17." (PMID 32028721, 2020).
inflammatory bowel disease (continued). "These animals were also shown to develop a spontaneous inflammatory bowel disease (IBD) associated with increased abundance of CD4+ T cells expressing the pro-inflammatory cytokines IL17, interferon gamma (IFNγ), and tumor necrosis factor alpha (TNF⍺) in the colonic lamina propria." (PMID 32598378, 2020). "Indeed, loss of Caspase‐8 or FADD induces TNF‐mediated necroptosis and inflammatory lesions in murine intestinal epithelium, resembling the pathology of inflammatory bowel disease." (PMID 33314666, 2020). "The effect of TNF-blockers on T-lymphocyte subsets is largely unknown in inflammatory bowel diseases (IBDs)." (PMID 32248339, 2020). "In people with inflammatory arthritis and inflammatory bowel disease, screening for tuberculosis (TB) and malignancy are performed and subjects with a history of latent or active TB are commenced on TB eradication treatment before starting TNF inhibitors." (PMID 32903555, 2020). "In particular, TNF-α plays a critical role in inflammatory bowel disease, where it can synergize with IFN-γ to regulate multiple tight-junction (TJ) proteins, including myosin light chain kinase, occludin, and ZO-1, as well as claudin-1 and claudin-2 (106, –, 109), which are also regulated by IL-17." (PMID 32958528, 2020). "Anti-TNF therapies have transformed the care of patients with inflammatory bowel disease (IBD)." (PMID 32483692, 2020). "We found that infliximab, a chimeric monoclonal antibody and a biological drug that works against TNF-α and is widely used to treat autoimmune diseases, such as inflammatory bowel disease and multiple sclerosis, efficiently blocks the necroptosis of EC in vitro and in vivo." (PMID 31221990, 2019). "However, TNFα signalling is also supposed to play a critical role for the pathogenesis of inflammatory bowel disease (IBD), infectious diseases, intestinal wound healing and tumour formation." (PMID 30995806, 2019). "Secondary cytokines such as TNF-α, IL-1β, and IL-6 are known to increase the presence of inflammatory cells in the colon tissue in response to primary Th1/Th17 immune responses in inflammatory bowel disease (IBD) thereby synergistically drawing the inflammatory milieu." (PMID 31683524, 2019). "Interestingly, we identified TNFα as such a gene, which is a relevant therapeutic target in RA, ankylosing spondylitis and inflammatory bowel diseases." (PMID 31216336, 2019). "Furthermore, osteocyte sclerostin is elevated in animal models of high fat diets with elevated serum and osteocyte TNF-α, inflammatory arthritis, periodontitis alveolar bone, spinal cord injury, and inflammatory bowel disease." (PMID 31139147, 2019). "V565 is an engineered TNFα-neutralising single domain antibody formulated into enteric coated mini-tablets to enable release in the intestine after oral administration as a possible oral treatment for inflammatory bowel disease (IBD)." (PMID 31575982, 2019). "Furthermore, intrathecal injection of minocycline or the TNF-α antibody reduced pain behaviors in animal models of inflammatory bowel disease." (PMID 31653262, 2019). "Treatment with MaR1 also reduced 2,4,6-trinitrobenzenesulfonic acid- and dextran sulfate sodium-induced inflammatory bowel disease by reducing the production of cytokines such as tumor necrosis factor-α (TNFα), IL-1β, IL-6 and interferon-γ (IFNγ) depending on the stage of the disease." (PMID 30816324, 2019). "TNFα is an important cytokine in inflammatory bowel disease." (PMID 29563546, 2018). "Nine out of 17 patients had steroids (5–20 mg/d), one had additional anti-TNF-α treatment due to inflammatory bowel disease (XX.II.1), one had additional daclizumab due to MS (CZ.II.2), and two had received abatacept (CTLA4-Fc) additionally in order to ameliorate the CTLA-4 insufficiency." (PMID 30250467, 2018).
inflammatory bowel disease (continued). "A previous study has shown that IL-10−/− mice that develop a form of inflammatory bowel disease (a model for Crohn’s disease) gained more weight and developed lower pathological scores, lower TNF-α concentrations, and lower SAA content when mice were fed a TGFβ-2-containing diet." (PMID 29675026, 2018). "The mechanism of Portulaca extract in alleviation of inflammatory bowel disease could be related to its regulation of inflammatory cytokines (TNF-α, IL-6, and IL-1β), transcription factors (NF-kB and PPAR-γ), and apoptosis." (PMID 29483924, 2018). "Similarly, the Canadian Child Inflammatory Bowel Disease Network has reported that 61% of patients with CD are maintained on an anti-TNF therapy, compared with 31% of UC patients." (PMID 30009157, 2018). "Inflammatory bowel disease is effectively treated with anti-TNF-α monoclonal antibody (Infliximab), either as monotherapy or in combination with other immunomodulators, and current efforts are directed toward the crucial goal of achieving MH in order to accomplish long-term remission." (PMID 29312336, 2017). "However, according to a recent large cohort multicenter study in 873 inflammatory bowel disease patients receiving TNF antagonists in Korea, the adjusted SIR was 41.7 compared with that of a age and sex matched sample of the general population." (PMID 28743918, 2017). "An abundance of different cytokines, including IL-6 and TNF-α, can lead to inflammation, which can in turn lead to several diseases, including Alzheimer’s disease, cardiovascular diseases, inflammatory bowel disease, sickness behavior, tumor progression, and so on." (PMID 28545436, 2017). "Interestingly, two of our patients were diagnosed with childhood TAK, while being treated with a TNF-α inhibitor for inflammatory bowel disease." (PMID 29166923, 2017). "With the advent of the biologic era over the last decade, drugs such as infliximab and other anti-tumor necrosis factor monoclonal antibodies have revolutionized the treatment strategy of inflammatory bowel disease (IBD), and novel biologic agents are still emerging." (PMID 28420140, 2017). "In particular, studies on human colonic epithelial cell lines as well as on intestinal tissues from patients with inflammatory bowel diseases revealed that inflammatory cytokines, such as TNF and IL-1β, promoted an up-regulation of NK1 receptor expression and a marked increase in SP release." (PMID 27295950, 2016). "Similarly, green tea polyphenols regulated both IFN-γ and TNF-α secretion in colon and lamina propria lymphocytes in a murine model of inflammatory bowel disease." (PMID 27187455, 2016). "Importantly, anti-TNF therapy is a mainstream treatment for patients with moderate to severe inflammatory bowel disease." (PMID 27447967, 2016). "Anti-TNF-α-induced psoriasiform dermatitis should be considered in the differential diagnosis when evaluating a new erythematous skin condition in an individual with a history of inflammatory bowel disease who is being treated with a TNF-α inhibitor." (PMID 27738572, 2016). "Forty-two pregnancies exposed directly to anti-TNF agents (35 with infliximab and 7 with adalimumab) were compared to 23 pregnancies before inflammatory bowel disease diagnosis, 78 pregnancies before starting infliximab, 53 pregnancies treated with infliximab, and 56 pregnancies of healthy women." (PMID 28044081, 2016). "Juvenile idiopathic arthritis (JIA) was the most frequent indication for anti-TNFα treatment (74.7 %, 195 treatments in 163 patients); other indications included inflammatory bowel disease (19.1 %, 50 treatments in 46 patients) and idiopathic uveitis (4.2 %, 11 treatments in 8 patients)." (PMID 26635208, 2015). "The Japanese Inflammatory Bowel Disease Research Group proposed a set of consensus statements in 2007, updated again in 2014, to address growing low-level evidence supporting the use of anti-TNF therapy." (PMID 26609459, 2015).
inflammatory bowel disease (continued). "Some diseases that generally improve with most TNF alpha inhibitors include inflammatory bowel disease such as ulcerative colitis and Crohn's disease (though etanercept is not effective in inflammatory bowel disease), as well as rheumatoid arthritis and psoriasis." (PMID 26664821, 2015). "However, TNFα, an inflammatory cytokine with a critical role in the pathogenesis of the inflammatory bowel diseases, has previously been shown to alter cellular morphology through its interaction with Rho signaling pathways." (PMID 24466350, 2014). "It was indeed recently demonstrated that anti-TNF antibodies induce IL-10 producing macrophages in an Fc-dependent manner and that these immunoregulatory macrophages are involved in mucosal healing in inflammatory bowel disease." (PMID 22563430, 2012). "More recently, it has been characterized as an inflammatory cytokine that is implicated in several pathologic intestinal conditions (e.g. colon cancer and inflammatory bowel disease) likely through induction of IL-1b, IL-6, IL-8, IL-12, TNFα, and other pro-inflammatory cytokines." (PMID 22829946, 2012). "We postulate that TNF contributes to a reduced mucosal and epithelial integrity as observed in inflammatory bowel diseases by perturbing and altering the mode of intestinal epithelial morphogenesis and, in this way, the functional differentiation of regenerative intestinal mucosa." (PMID 21853060, 2011). "Background/Objectives: There is limited data regarding the association of anti-drug antibody (ADA) levels with the efficacy of anti-tumor necrosis factor (anti-TNF) therapy in patients with inflammatory bowel disease (IBD)." (PMID 41598485, 2026). "Last but not least, refractory Inflammatory DiseasesRheumatoid arthritis (RA) and inflammatory bowel disease (IBD) involve localized overexpression of pro-inflammatory factors (TNF-α, IL-6) and oxidative stress." (PMID 41560795, 2026). "Excessive pro-inflammatory cytokines (e.g. tumor necrosis factor-alpha [TNF-α]) can reduce TJ protein expression and trigger mucosal hyperpermeability, a dysfunction implicated in inflammatory disorders such as post-weaning diarrhea in piglets or inflammatory bowel disease in humans." (PMID 40665732, 2026). "In our prospective, single-center pilot study, we enrolled patients with ulcerative colitis (UC), a chronic inflammatory bowel disease (IBD) in which tumor necrosis factor-α (TNF-α) activity is well documented even during remission." (PMID 41598825, 2026). "Elevated TNF-α also contributes to the pathophysiology of psoriasis and inflammatory bowel disease (IBD), as well as insulin resistance in type 2 diabetes." (PMID 41596763, 2026). "This may be linked to systemic inflammation known to be present in DMD given that a similar decrease in humanin expression has been observed in human growth plates cultured ex vivo with the proinflammatory cytokine TNF-alpha or serum from patients with inflammatory bowel disease." (PMID 41550496, 2026). "Inflammatory bowel disease (IBD), including Crohn s disease (CD) and ulcerative colitis (UC), is characterized by chronic intestinal inflammation driven by elevated tumor necrosis factor-alpha (TNF- α )." (PMID 41678027, 2026). "Anti-TNF agents may also be an alternative to colchicine, especially in patients with FMF with predominant joint involvement (persistent peripheral arthritis or spondyloarthritis) or associated inflammatory bowel disease (Crohn’s disease)." (PMID 41333465, 2025). "Finally, Gene Set Enrichment Analysis (GSEA) confirmed that the TNF signalling pathway, NF‐κB pathway, and inflammatory bowel disease pathway were significantly activated in ATF7−/− + DSS mice relative to WT + DSS controls, reinforcing the pro‐inflammatory phenotype associated with ATF7 loss." (PMID 40903840, 2025). "Failure of anti-TNF therapy is a real concern in children with inflammatory bowel disease (IBD) owing to the limited therapeutic arsenal." (PMID 40244207, 2025).